IL22 (interleukin 22)
Diseases named in the same sentence as IL22 in open-access papers (continued):
Sharing a sentence is not in itself a finding about the gene and the disease.
colon carcinoma (continued). "Both secreted and anchored mouse IL-22 produced by Lactobacillus was biologically active, as determined by its ability to induce IL-10 secretion in the Colo 205 human colon cancer cell line." (PMID 28830549, 2017). "We demonstrated that IL-22 enhances aerobic glycolysis via targeting hexokinase 2 (HK2) in colon cancer cells." (PMID 28445985, 2017). "IL-22 produced by ILC3s can contribute to development of colon cancer in a mouse model, consistent with the presence of IL-22-producing CD3− cells within human colorectal carcinoma tumors." (PMID 28271445, 2017). "Pro-inflammatory cytokine IL-22 was found to enhance aerobic glycolysis through a STAT3/c-Myc/HK2 signaling pathway in colon cancer cells." (PMID 28445985, 2017). "Numerous reports have elucidated that IL-22 is involved in tumorigenesis and tumor progression in liver, pancreatic and colon cancers." (PMID 28445985, 2017). "Cell growth assay revealed that knockdown of HK2 attenuated the promoting effect of IL-22 on colon cancer cell proliferation." (PMID 28445985, 2017). "In summary, our data has revealed that pro-inflammatory cytokine IL-22 enhances aerobic glycolysis through a STAT3/c-Myc/HK2 signaling pathway in colon cancer cells." (PMID 28445985, 2017). "In vitro, interleukin-22 enhanced glucose consumption and lactate production via targeting hexokinase-2 in colon cancer cells." (PMID 28445985, 2017). "Here, we show that aberrant interleukin-22 expression facilitates aerobic glycolysis in colon cancer cells." (PMID 28445985, 2017). "Elevated interleukin-22 mRNA expression was observed and positively correlated with hexokinase-2 in colon cancer tissues." (PMID 28445985, 2017). "Specifically, IL-22 was found to activate STAT3 in human colon cancer cells, resulting in the expression of the H3K9-specific N-methyltransferase DOT1L, which subsequently induced the expression of core stem cell genes such as SOX2, NANOG, and POU5F1." (PMID 28492497, 2017). "Previous studies in animal models of colorectal carcinoma have established Th17 cells, IL-22, and IL-23 as important drivers of inflammation leading to colonic tumor formation." (PMID 27165713, 2016). "Previous studies revealed the activation of the antiapoptotic protein Bcl-xL by IL-22 in lung cancer, colon cancer and hepatocarcinoma cells." (PMID 25793261, 2015). "IL-22 was reported to induce REG Iα transcription via STAT3 activation in human colon cancer cells and to induce Reg I and Reg II in NOD mouse islets." (PMID 25767811, 2015). "IL-22 has been shown to support the growth of mantle cell lymphoma, anaplastic large cell lymphoma, hepatocellular carcinoma and colon carcinoma through STAT3 activation." (PMID 23667456, 2013). "Secondly, we reported for the first time that excessive IL-22 also was present in human colon cancer." (PMID 23379788, 2013). "IL-22 can also promote intestinal disease by enhancing epithelial cell proliferation leading to colon cancer." (PMID 23508190, 2013). "In correlation with overexpression of IL-22 in TILs of CC, IL-22RA1 is also overexpressed in colon cancer cells and in IECs of UC, which ensures the transmission of the IL-22 signal." (PMID 23379788, 2013). "Hct-116, a colon cancer cell line, was co-transplanted with TILs isolated from two CC patients with different IL-22 expression levels according to analysis by FCMs." (PMID 23379788, 2013). "In order to investigate the expression of IL-22 in human colon cancer, tumor infiltrated leukocytes (TILs), which are the principal source of IL-22, were isolated from excised fresh tumor tissues." (PMID 23379788, 2013). "ILC3-produced IL-22 may induce abnormal proliferation of IECs and thus function in the transition from chronic inflammation to colon cancer as well as the perpetuation of cancer." (PMID 41467015, 2025).
colon carcinoma (continued). "IL-36γ, together with IL-17α or IL-22, synergistically induces the expression of different genes involved in the IL-17/IL-23 axis and additively induces colon cancer cell proliferation, supporting a tumor-promoting role for inflammatory factors, such as IL-22 and IL-36, in CRC." (PMID 39073546, 2024). "In addition, a study showed that the reduction in IL-17 and IL-22 can prevent the development of invasive colon cancer in mouse models of inflammatory dysplasia." (PMID 37304260, 2023). "The observation that IL-22 is related to the development of human colon cancer could be explained by the hypothesis that the same pathways that are critically involved in wound healing processes, once dysregulated, may favor tumorigenesis." (PMID 37296855, 2023). "However, in a model of bacteria-induced colon cancer, it was demonstrated that IL-17 and IL-22 from ILCs in the colon contributed to the development of the colon cancer." (PMID 36768726, 2023). "Further work would be required to verify the causal involvement of IL-22, a cytokine with pleiotropic effects in the gut mucosa, in colonic tumor formation in the absence of NHE3." (PMID 36042372, 2022). "It has been demonstrated that IL-22 and IL-22R were overexpressed in colon cancer microenvironment." (PMID 34941188, 2021). "Similar to the differential microbiota results, systemic inflammatory cytokines were positively correlated with the colon cancer process, and key protein levels of LPS, IL-6, IL-22 and IL-17A in mouse serum were significantly higher after modelling than in the sham group (p < 0.01 or p < 0.01)." (PMID 34531745, 2021). "Microbial cells and flagellin extracted from fecal samples of 61 healthy donors modulated the viability of the human (HT29) colon carcinoma cells and the host response through the stimulation of the expression of Toll-like receptor 5, lectin RegIIIα and three interleukins (IL-8, IL-22 and IL-23)." (PMID 32144387, 2020). "Moreover, IL-22 mediated drug resistance has also been observed in 5-Fluorouracil and Oxaliplatin treated colon cancer cell lines." (PMID 33042126, 2020). "However, the high expression of LINC00662 up-regulated the protein levels of CLDN8 and IL22 in colon cancer cells and activated ERK signaling pathway were markedly reversed by miR-340-5p overexpression." (PMID 31900207, 2020). "Moreover, IL-22 was recently shown to protect intestinal stem cells against genotoxic stress and thus against colon cancer." (PMID 32477345, 2020). "INC00662 may be a potential proto-oncogene by regulating the co-expression of CLDN8/IL22 through competitively binding to miR-340-5p to affect the occurrence and development of colon cancer." (PMID 31900207, 2020). "Since the TH22-related cytokine IL-22 has been reported to promote tumorigenesis in distinct cancer entities, including lung, ovarian, breast, gastric, pancreatic, and colon cancers, the IL-22-IL-22R1 pathway has become an attractive target for anticancer therapy." (PMID 31637216, 2019). "Pro-tumor: ILC3s sustain colon cancer via production of IL-22." (PMID 32117199, 2019). "We speculated that aberrant expression of IL-22 may be involved in glucose metabolism reprogramming in colon cancer cells." (PMID 28445985, 2017). "Further, HK2 may be a potential target for therapy in colon cancer with aberrant expression of IL-22." (PMID 28445985, 2017). "Therefore, for the first time, our study has identified IL-22 as an important regulator of metabolic reprogramming in colon cancer cells." (PMID 28445985, 2017). "Since our results had clearly demonstrated that IL-22 enhanced aerobic glycolysis via targeting HK2 in colon cancer cells, we further explored whether HK2 accounts for IL22-mediated cancer cell proliferation." (PMID 28445985, 2017). "IL-22 also enhances tumor growth and metastasis in both colon cancer and pancreatic adenocarcinoma." (PMID 25793261, 2015). "We sought to investigate the role of IL-22 expression in colon cancer (CC)." (PMID 23379788, 2013).
colon carcinoma (continued). "Interestingly, constitutive deletion of the IL-22 antagonist molecule IL-22BP in mice does not result in more tumor formation in steady state conditions but in the context of chronic colitis the unrestrained IL-22 signaling results in increased incidence of colon tumors." (PMID 33692792, 2021). "Moreover, IL-23-deficient mice are resistant to tumor formation, and the depletion of ILCs and IL-22 can reverse established tumors in a Rag1−/− mouse tumor model induced by Helicobacter hepaticus oral infection, indicating that ILCs and IL-22 are essential for the formation of colonic tumors." (PMID 31781671, 2019). "To further define the role of key TH17 cytokines in inhibiting chemokine expression, we treated human epithelial colon cancer cells (HCT116) with recombinant IL-17A and IL-22 and then determined the chemokine expression after DSS treatment." (PMID 40749055, 2025). "Through western blot assay, we found that the high expression of LINC00662 significantly increased the expression of CLDN8 and IL22 in protein level and activated the ERK signaling pathway in colon cancer cells." (PMID 31900207, 2020). "The luciferase activity of Luc-IL22–3′UTR was enhanced in colon cancer cells with LINC00662 over-expression, but the luciferase activity of Luc-IL22–5’UTR or Luc-IL22- CDS was unaffected." (PMID 31900207, 2020). "This study evaluated the effects of IL-20, IL-22, and IL-24 in epithelial renewal using the LS174T human colon cancer epithelial cell line." (PMID 31311100, 2019). "IL-22 has been shown to activate STAT3 signaling and further enhance the development of colon cancer." (PMID 30894857, 2019). "A high dose of IL-22 activates Erk1/2, JNK, and p38 MAP kinase in a rat hepatoma cell line and human colonic cancer cell line HT29." (PMID 29075900, 2018). "Therefore, it is uncertain whether IL-22 plays the role of a potential promoter in colon cancer." (PMID 21625390, 2011). "Both IL22 and CLDN8 are target genes of miR-340-5p and are co-expressed in colon cancer cells." (PMID 31900207, 2020). "Regarding the role of TH22/IL-22 in CRC, in vitro studies have shown that IL-22 enhances nitric oxide synthase expression in colon cancer cells, significantly contributing to conversion to nitrites, which are associated with colonic inflammation and carcinogenesis." (PMID 31637216, 2019). "Also in the present study, our result showed that HK2 overexpressed in colon cancer tissues and knockdown of HK2 attenuated the stimulatory effect of IL-22 on glucose utilization and lactate production in DLD-1 cells." (PMID 28445985, 2017). "Other studies have clarified the presence of cytokine (IL-6 and IL-22)-responsive elements in the promoter regions of REG Iα and Iβ and HIP/PAP in pancreatic or colon cancer cells, although it remained unclear whether STAT3 and/or other transcriptional factors actually bind to these elements." (PMID 31780871, 2019). "IL-22 could significantly prolong the survival of mice bearing Colon 26 cells, though it did not inhibit the growth of colon cancer cells." (PMID 21625390, 2011).
dermatitis (61 papers, 2012 to 2025). An inflammatory process affecting the skin. "In an imiquimod-induced psoriasis model, AhR deficiency exacerbates skin inflammation with upregulated gene expression of Il22, Il17a, and Il23." (PMID 31683543, 2019). "In fact, several skin disorders are characterized by unbalanced KCs proliferation and differentiation caused by increased inflammatory environment enriched by IL-22." (PMID 30858525, 2019). "In mouse models of psoriasis, clock gene mutations changed skin inflammation by modulating IL-23 receptor expression in gamma delta T cells and subsequent IL-17 and IL-22 production and treatment with a REVERB agonist suppressed IL-17 production in gamma-delta T cells and improved dermatitis." (PMID 36865523, 2022). "In addition to Th2 deviation, IL-22 produced by Th22 cells is also linked to the chronicity and amplification of skin inflammation in AD." (PMID 34198894, 2021). "Hence, the fine-tuning of IL-22 signaling implicated in these processes can be beneficial to treat skin disorders." (PMID 30858525, 2019). "When these findings are considered together, CD103+ dDCs and IL-17A- and IL-22-secreting skin-resident T cells may be associated with skin inflammation in Nfkbiz−/− mice." (PMID 28740238, 2017). "The results showed that CBG improved dermatitis severity score, epidermal thickness, and mast cell count and reduced inflammatory cytokines (Tslp, Il1b, Il4, Il6, Il13, Il17, Il18, Il22, and Il33) by qRT-PCR (p < 0.001)." (PMID 39851511, 2025). "In a mouse model of imiquimod-induced psoriasis-like dermatitis, IL-17 and IL-22 secreted from γδ T cells and Th17 upon IL-23 stimulation were involved in skin inflammation and keratinocyte activation, which were improved by TYK2 inhibitor treatment." (PMID 38351043, 2024). "Further studies are required to elucidate the mechanisms of Th22 cells in the pathogenesis of different diseases, as well as explore therapeutics targeting the Th22/IL-22 signaling pathway in skin disorders." (PMID 35911703, 2022). "Emerging evidences have suggested that Th22 cells and IL-22 can play either protective or pathogenetic roles in various skin disorders." (PMID 35911703, 2022). "TARC and IL-22 are related to skin inflammation, and their mRNAs are expressed at high levels in AD lesions." (PMID 34454603, 2021). "Antibiotic treatment in an imiquimod-induced model has been shown to result in milder dermatitis, due to a background of reduced IL-22+γδ T-cells in the skin as well as reduced Th17 cells in the gut." (PMID 32392785, 2020). "Imiquimod-induced dermatitis is attenuated in Il1r–/– mice, as is induction of IL-17 and IL-22 secretion." (PMID 32917058, 2020). "Taken together, these results suggest that IL-6 acts to ameliorate epidermal hyperplasia during skin inflammation by reducing IL-22-induced keratinocyte proliferation." (PMID 31781680, 2019). "In a murine dermatitis model, topically applied FICZ activated AHR and significantly reduced the dermatitis score and histological inflammation with a decrease of Il22 gene expression in chronic mite antigen-induced dermatitis." (PMID 31683543, 2019). "Antibiotic treatment relieved the dermatitis in Nfkbiz−/− mice, accompanied by decreased numbers of IL-17A- and IL-22-secreting CD4+ T cells." (PMID 28740238, 2017). "In this study, we showed that spontaneous dermatitis developed in Nfkbiz−/− mice along with expansion of IL-17A- and IL-22-secreting CD4+ T cells." (PMID 28740238, 2017). "According to the literature, the IL-1β facilitates specific inflammatory mechanism of IL-22 in the skin disorders." (PMID 29312598, 2017). "Instead, the increased severity of skin inflammation was mainly attributed to significant increase in skin IL-22-producing T cells especially TCRγδ+IL-22+ cells." (PMID 26416167, 2015). "IL-22 and IL-17A are also necessary for epidermal hyperplasia in this model, as dermatitis was greatly reduced in IL-22 KO or IL-17A KO mice." (PMID 22229105, 2012).
dermatitis (continued). "In imiquimod-induced dermatitis, IL-17A, IL-17F, and IL-22 may be mostly derived from Th17 cells or γδT17 cells, while CXCL1, CXCL2, CCL20, and IL-17C may be mainly produced by epidermal keratinocytes." (PMID 37762500, 2023). "In addition, there was an increasing trend in type 3 cytokines such as IL-17A and IL-22, suggesting an effect of skin inflammation, tissue repair, and infection on the production of anti-microbial peptides." (PMID 38203647, 2023). "For instance, topical application of the tryptophan metabolic derivative FICZ could reduce the gene expression of IL-22 in a murine mite-induced dermatitis model by activating AhR receptors." (PMID 38318507, 2023). "Additionally, skin-specific IL-22 transgenic (K5-tTA-IL-22) mice exhibited chronic pruritic dermatitis with increased IL-4, IL-13, and gastrin-releasing peptides, along with elevated susceptibility to S. aureus infections." (PMID 35911703, 2022). "Taken together, Th22 cells and IL-22 play essential roles in in the pathogenesis of skin disorders." (PMID 35911703, 2022). "In contrast to its skin integrity protective function, excessive IL-22 can lead to skin disorders." (PMID 35911703, 2022). "IL-22 also induces dermatitis and acanthosis by activating the STAT3-mediated IL-23 pathway." (PMID 34295334, 2021). "Moreover, the chemical inhibitor of AHR (CH-223191) was effective in the control of skin inflammation induced by intradermal administration of IL-23, blocking the secretion of IL-22 by Th17 and dermal γδ T cells." (PMID 34831399, 2021). "IL-17 and IL-22 enhance skin inflammation via the ROS-NLRP3-caspase-1 pathway." (PMID 32528469, 2020). "IL-22 is a proinflammatory cytokine that promotes skin inflammation and epidermal hyperplasia." (PMID 31781680, 2019). "Results from this work suggests that IL-6 might play a role in regulating the IL-22/IL-22Rα system during skin inflammation." (PMID 31781680, 2019). "It is interesting to note that the relationship between IL-6 and the IL-22/IL-22Rα system in the context of skin inflammation is unknown." (PMID 31781680, 2019). "In the context of skin inflammation, inflammatory cytokines such as TNF-α, IL-17A, and IL-22 induce keratinocytes to produce proinflammatory cytokines, including IL-1β, IL-6, TNF-α, and IL-23, which subsequently influence the liver to increase SAA production." (PMID 39519167, 2024). "The HFD decreased mRNA expression of IL-17A, IL-17F, IL-22, TNF-α, IL-1β, CXCL1, CXCL2, and keratin 16, and increased mRNA expression of TGF-β1 and CDKN1A in imiquimod-induced dermatitis." (PMID 37762500, 2023). "Oral propionate reduced inflammatory infiltrates and epidermal Ki67+ cells and reduced mRNA levels of IL-17A, IL-17F, IL-17C, IL-22, IL-1β, IL-6, TNF-α, CXCL1, CCL20 and increased those of TGF-β1and IL-10 in imiquimod-indued dermatitis." (PMID 37762500, 2023). "Oral propionate and the HFD reduced mRNA expression of IL-17A, IL-17C, IL-17F, IL-22, IL-1β, IL-6, TNF-α, CXCL1, CXCL2, and CCL20 in imiquimod-induced dermatitis." (PMID 37762500, 2023). "Oral propionate decreased mRNA expression of IL-17A, IL-17C, IL-17F, IL-22, IL-6, IL-1β, TNF-α, CXCL1, and CCL20 in imiquimod-induced dermatitis in comparison between NDIS versus NDIP." (PMID 37762500, 2023). "Further, ILC3-derived IL-22 induces an upregulation of MHC-II on keratinocytes, which promotes T cell polarization and skin inflammation, demonstrating a key circuit mediating skin inflammation." (PMID 35359972, 2022). "Attenuates IMQ-psoriasiform skin inflammation by increasing FLG expression and reducing IL-17 and IL-22 levels.Exacerbates the DTH response by promoting Th17 cells." (PMID 34831399, 2021). "Using the model of IL-23-induced skin inflammation, we demonstrated that CD69 expression controls AHR-mediated IL-22 expression in Th17 and γδ T cells." (PMID 34831399, 2021).